ANKRD62 (ankyrin repeat domain 62)
Synonyms: DKFZp779B1634
Tractability: PROTAC: ubiquitination databases record sites on it.
Gene: Protein-coding gene on chromosome 18 (12,093,843 to 12,129,764, forward strand). Ensembl gene ENSG00000181626.
Subcellular location (Human Protein Atlas): Nuclear bodies; Nucleoplasm; Actin filaments
Genetic constraint (gnomAD): Loss-of-function variants: 44 observed, 60.03 expected, observed/expected ratio (o/e) 0.73, 90% interval 0.57 to 0.94. The upper end of that interval is the gene's LOEUF score, 0.94, which puts it in group 3 of 6, group 1 being the genes least tolerant of losing a copy. Missense variants: 790 observed, 808.39 expected, observed/expected ratio (o/e) 0.98, 90% interval 0.92 to 1.04. Synonymous variants: 291 observed, 282.55 expected, observed/expected ratio (o/e) 1.03, 90% interval 0.94 to 1.13.
Homologues: Orthologues: chimpanzee ANKRD62 (98% identical), macaque ANKRD62 (85% identical), Caenorhabditis elegans lem-3 (11% identical), Drosophila melanogaster CG8679 (10% identical), Caenorhabditis elegans F44E5.15 (5% identical), Drosophila melanogaster CG42391 (2% identical), Caenorhabditis elegans K07D4.2 (2% identical). Paralogues in human: ANKRD26 (54% identical), ANKRD30B (34% identical), ANKRD30A (34% identical), ANKRD20A1 (31% identical), ANKRD18B (27% identical), ANKRD18A (26% identical), ANKRD30BL (10% identical).
Diseases named in the same sentence as ANKRD62 in open-access papers:
ANKRD62 is named in the same sentence as 2 diseases in open-access papers, as found by Europe PMC text mining. Sharing a sentence is not in itself a finding about the gene and the disease.
ANKRD62 shares sentences with these, for which no sentence is quoted: cancer (1 paper); ovarian yolk sac tumor (1).